TLR4 (toll like receptor 4)
Diseases named in the same sentence as TLR4 in open-access papers (continued):
Sharing a sentence is not in itself a finding about the gene and the disease.
endometriosis (continued). "Increased numbers of Escherichia coli and higher levels of bacterial endotoxin are observed in the menstrual blood of women with endometriosis compared with control women, leading to the Toll-like receptor 4 (TLR-4)-mediated proliferation of endometriotic lesions." (PMID 36900012, 2023). "In the same year, another study reported that the expression of TLR4 and TLR2 were higher in the endometrial tissues from endometriosis patients than that of normal endometrium, suggesting the potential role of TLR2 and TLR4 in the development of endometriosis." (PMID 37033937, 2023). "In addition, the HMGB-1/TLR4/NF-κB axis can also induce the proliferation and invasion of endometriotic cells and contribute to endometriosis-induced pain 52-54." (PMID 35864971, 2022). "In addition, endometriosis-activated astrocytes and microglia with upregulated TLR4-Myd88 signaling in the spinal dorsal horn." (PMID 33673857, 2021). "However, the specific role of TLR4 signaling in the pain symptom of endometriosis (EM) remains obscure." (PMID 33673857, 2021). "Also, endometriosis upregulated the expression of TLR4 and Myd88 in small-diameter nociceptors with increased phosphorylation of NF-κB in the DRG." (PMID 33673857, 2021). "Some studies have shown that TLR4 expression is decreased in patients with endometriosis." (PMID 32916976, 2020). "Recent studies pointed out the involvement of the LPS/TLR4 cascade in the growth regulation in endometriosis tissues, since LPS/TLR4 dysfunction may impair the correct mechanism of immune response and favor the onset and progression of the disease." (PMID 32349318, 2020). "One study also shows that TLR3 and TLR4 expression is decreased in patients with endometriosis." (PMID 32751735, 2020). "Therefore, we postulate that Barnesiella may exert a protective effect against endometriosis by modulating the LPS/TLR4/NF-kB pathway to inhibit the initiation and progression of endometriosis." (PMID 39027094, 2024). "The presence of LPS may contribute to TLR4-mediated growth of endometriosis." (PMID 38974388, 2024). "Blockade of TLR4 and MyD88 might serve as a potential treatment for pain in endometriosis." (PMID 33673857, 2021). "Among these, SNPs in the coding and promoter regions of the human TLR4 gene have been demonstrated to induce a dysregulated TLR4 signaling pathway, this directly correlated to various infectious, autoimmune, allergic, inflammatory diseases, and lastly, endometriosis." (PMID 32349318, 2020). "A murine endometriosis model was established in wild-type C57BL/6 and TLR4-/- mice treated with TAK-242." (PMID 42123727, 2026). "TLR4 and RAGE expression in peritoneal fluid macrophages inversely correlate with endometriosis severity (human)." (PMID 40508002, 2025). "This study aimed to demonstrate that HMGB-1 and its receptors, TLR4 and RAGE, play important roles in the changes in the follicular environment in infertile patients with endometriosis." (PMID 41226929, 2025). "In the case of differentiation between endometriosis phenotypes, AUC values ≥ 0.85 were obtained for CD8 + TLR3, CD4 + TLR4, and CD19 + TLR3 in the comparisons of PE vs. CC and DIE vs. CC, suggesting their importance in distinguishing these disease subtypes." (PMID 40862752, 2025). "We observed markedly higher expression of TLR2, TLR3, TLR4, TLR7, TLR8, and TLR9 on CD4+, CD8+, and CD19+ lymphocytes in the endometriosis group, indicating their active participation in modulating immune responses in the disease setting." (PMID 40862752, 2025). "Notably, in the case of TLR4 expression, significant differences were also found between specific disease subtypes—particularly between cesarean section scar endometriosis (CC) and deeply infiltrating endometriosis (DIE)—suggesting distinct patterns of immunopathogenesis." (PMID 40862752, 2025).
endometriosis (continued). "It appears that NF-kB inhibitors and TLR4 agonists lead to the suppression of HMGB1 and decreases in IL-6 levels, demonstrating their involvement in endometriosis and the clinical relevance of this new finding." (PMID 38337827, 2024). "E2 promotes the initial inflammatory mediator, LPS/TLR4, signaling to directly stimulate peritoneal macrophages to secrete TNF-α and IL-6 in the internal milieu of pelvic inflammation within endometriosis." (PMID 37226177, 2023). "The authors suggest that a substantial amount of endotoxin in the peritoneal fluid, related to menstrual blood reflux, would be involved in pelvic inflammation and promote Toll-like receptor 4- (TLR4-) mediated growth and progression of endometriosis." (PMID 38601772, 2023). "TLR4, TLR3 and TLR2 are members of the TLR family, mostly found in samples studied for endometriosis." (PMID 37446108, 2023). "Immunohistochemical analysis of endometriotic tissues showed that TLR3, TLR4, and MYD88 were localized in endometriosis lesions." (PMID 36093086, 2022). "In endometriosis, we can observe a significant decrease in TLR3 and TLR4 mRNA levels in eutopic tissues collected during the proliferative phase, when compared to controls (P < 0.05)." (PMID 18775079, 2008). "In endometriosis, eutopic tissues revealed weaker staining for TLR3 and TLR4 proteins when compared to controls." (PMID 18775079, 2008). "Pharmacological inhibition of TLR4 attenuates lesion growth, supporting TLR4 as a promising non-hormonal therapeutic target for endometriosis." (PMID 42123727, 2026). "Beyond TLR4, TLR2 also appears to play a significant role in the pathogenesis of endometriosis." (PMID 40862752, 2025). "The antagonist of TLR4 (LPS-RS-Ultra, LRU) and MyD88 homodimerization inhibitory peptide (MIP) were intrathecally administrated to assess the behavioral effects of blocking TLR4 signaling on endometriosis-related pain." (PMID 33673857, 2021). "However, our results indicated that expression of TLR4 in follicular cells of women with endometriosis was not significant compared to the control." (PMID 33209739, 2020). "Additionally, gut-derived LPS from Gram-negative bacteria such as E. coli activates Toll-like receptor 4 (TLR4), triggering the increased production of pro-inflammatory cytokines including TNF-α, IL-6, and IL-1β—all of which are elevated in the peritoneal fluid of individuals with endometriosis." (PMID 40430189, 2025).
Crohn disease (50 papers, 2009 to 2026). A gastrointestinal disorder characterized by chronic inflammation involving all layers of the intestinal wall, noncaseating granulomas affecting the intestinal wall and regional lymph nodes, and transmural fibrosis. "The direct relevance of this system to IBD is reinforced by the recent identification of a functional missense variant in the LPS receptor, TLR4, associated with Crohn’s disease." (PMID 28263993, 2017). "Genotypic and allelic distribution of TLR4 rs4986791 polymorphism in Malaysian Crohn’s disease (CD) patients and control individuals." (PMID 27069792, 2016). "TLR4 Thr399Ile polymorphism: Genotype and allele frequencies (%)in Crohn's disease (CD) patients and controls." (PMID 19664207, 2009). "TLR4 Asp299Gly polymorphism: Genotype and allele frequencies (%) of in Crohn's disease (CD) patients and controls." (PMID 19664207, 2009). "In this study, we sought to determine whether TLR4 gene was associated with Crohn's disease (CD) among the Tunisian population and its correlation with clinical manifestation of the disease." (PMID 19664207, 2009). "Additionally, in contrast to the dogma, we find that the major Crohn’s disease-associated NOD2 mutations could cause a primarily immunodeficient phenotype by selectively impairing TLR4-mediated IL-12 production and host defense." (PMID 26153766, 2015). "A follow-up study revealed that macrophages isolated from patients carrying the Crohn's disease-associated ATG16L1 mutant T300A produced more IFN-β when stimulated with the ligand poly (I: C) for TLR3 and the ligand LPS for TLR4." (PMID 39883213, 2024). "IAP and TLR4 colocalization has previously been investigated in intestinal resection specimens from patients with Crohn's disease." (PMID 38745834, 2024). "As research progresses, more and more autophagy-related Crohn's disease susceptibility genes have been identified, such as IRGM, ULK1, LRRK2, TLR4, etc.." (PMID 39883213, 2024). "Using the DGIdb database, four key NLRP3 inflammasome-related genes (APP, HSP90AB1, NFKB and TLR4) were further selected as potential druggable targets for Crohn’s disease treatment." (PMID 36685554, 2022). "TLR-4 and IL-1β are overexpressed in the intestinal epithelium of patients with Crohn's disease (diarrhoea)." (PMID 32733972, 2020). "The cellular localization of specific TLRs also changes in pathological conditions, as demonstrated in patients with active Crohn’s disease in which the basolateral expression of TLR4 in the colonic IECs is shifted to an apical position." (PMID 29438282, 2018). "NOD2/CARD15, TLR4 and CD14 mutations in Scottish and Irish Crohn's disease patients: evidence for genetic heterogeneity within Europe?" (PMID 28819537, 2017). "In two independent cohorts the TLR4 Asp299Gly SNP was found to be significantly higher in patients with Crohn’s disease." (PMID 23730203, 2012). "Crohn’s disease has received a large amount of interest with respect to the TLR4 Asp299Gly and Thr399Ile SNPs." (PMID 23730203, 2012). "TLR4 is up regulated in the intestinal epithelial cells in patients with ulcerative colitis and Crohn's disease (CD)." (PMID 19664207, 2009). "There was also enhanced expression of TLR-4 in crypt cells from ileal Crohn's disease." (PMID 24828022, 2014). "However, TLR4 and NOD2 were significantly associated with susceptibility to Crohn's disease in children in single gene analysis and gene-gene interactions." (PMID 23691182, 2013). "The co-existence of several allelic variant of TLR4, NOD2/CARD15 and HSP70-2 genes may be associated with severe form of the Crohn's disease among the Tunisian population." (PMID 19664207, 2009). "Additionally, increased expression of TLR3 and TLR4 was reported in RA patients and TLR4 was upregulated in Crohn’s disease, suggesting GLI3 may regulate the pathology of Crohn’s disease and RA through modulation of IL-6." (PMID 35937499, 2022).
Crohn disease (continued). "L. reuteri 6475 can inhibit TNF-α, a pro-inflammatory cytokine, in monocyte-derived macrophages isolated from children with Crohn’s disease, as well as toll-like receptor (TLR) 2 and TLR4-activated human and murinemonocytoid cell lines." (PMID 35966270, 2022). "Its role in Crohn’s disease has been supported by the production of a proinflammatory polysaccharide, which increases the production of TNF-α by interacting with the toll-like receptor 4 (TLR4) of immune cells (e.g., dendritic cells)." (PMID 36232581, 2022).
Salmonella Infections (50 papers, 2009 to 2025). Infections with bacteria of the genus SALMONELLA. "Research has revealed an association between TLR4-MyD88 dependent pathway-related gene expression and Salmonella infection." (PMID 32075044, 2020). "Tlr4-deficient mice show very high susceptibility to Salmonella infection due to a defective response to LPS." (PMID 29703142, 2018). "TLR4 plays an essential role in the innate immune response and hence is likely to be involved in young chickens at risk of Salmonella infection." (PMID 28848530, 2017). "TLR4 plays an important role in the murine Salmonella model as TLR4-deficient mice have increased susceptibility to Salmonella infection, and stimulation of TLR4 by LPS contributes to the development of septic shock during murine S. Typhimurium infection." (PMID 25860480, 2015). "The results from this study support the concept that TLR4 is an important modulator associated with the porcine response to Salmonella infection in swine." (PMID 24566961, 2014). "TLR4-deficient mice have increased susceptibility to Salmonella infection, and stimulation of TLR4 by LPS has an important role in the development of septic shock during S. Typhimurium infection." (PMID 23055923, 2012). "Indeed, chicken TLR4 polymorphisms have been associated with varia susceptibility to Salmonella infection." (PMID 41389540, 2025). "Many genes such as Major Histocompatibility Complex (MHC), Caspase1, NRAMP Family, inducible nitric oxide synthase (iNOS), those encoding complement proteins and Toll-like Receptor 4 (TLR4) have been found to be associated with resistance against Salmonella infection in poultry." (PMID 29884179, 2018). "For instance, L. paracasei inhibited the increase in TLR4 caused by Salmonella infection." (PMID 24733511, 2014). "TLR2 and TLR4 signaling plays a role in regulating the immunomodulatory functions of FRCs, enabling these cells to orchestrate peritoneal immunity in mouse Salmonella infection." (PMID 38827745, 2024). "In partial support of this notion, a previous report investigating Salmonella infection in chickens found a regulated expression of TLR4 in eosinophils and mast cells that were recruited to bursa post-infection." (PMID 36985344, 2023). "Salmonella infection, for example, can promote TLR4/ MyD88 pathway activation and consequent increases in macrophage and neutrophil infiltration." (PMID 35123464, 2022). "Mice overexpressing TLR4 show greater protection against Salmonella infection because of their improved control of bacterial growth in target organs and the increased expression of important immune response genes in their spleen." (PMID 33966642, 2021). "Chickens in the antibiotic and synbiotic supplemented groups had decreased cecal tonsil TLR-4 mRNA content compared to the control groups post-Salmonella infection throughout the study." (PMID 31600299, 2019). "Previous research has shown that the expression of genes related to the TLR4-MyD88-dependent pathway slightly increased on the first and third day after Salmonella infection in the caecum." (PMID 31795199, 2019). "In summary, our data suggest that M. alba L. activated macrophages via TLR4 to provide protection against Salmonella infection, indicating that M. alba L. modulates the effector functions of immunocompetent cells." (PMID 29545736, 2018). "Significant advances in understanding the host response to Salmonella infection have been made over the years with the identification of genes such as Slc11a11 (Nramp1), Tlr4 and Btk, first in the mouse model and later in other animal species." (PMID 29703142, 2018). "Salmonella infection via the stimulation of Toll-like receptor 4 has been shown to stimulate macrophages to hemophagocytosis, a process that lead to the phagocytosis of red and white blood cells." (PMID 28507548, 2017).
Salmonella Infections (continued). "The wild-derived mouse strain, MOLF/Ei is also susceptible to infection despite carrying functional copies of genes known to be important in Salmonella infection, such as Slc11a1 and Tlr4 (toll-like receptor 4)." (PMID 25161653, 2014). "It is known that TLR4 plays a significant role in the host defences against Salmonella infection in vivo." (PMID 21813005, 2011). "Although in chickens LPS can be sensed via the TLR4 receptor, the role of chicken TLR4 in Salmonella infection has been contradictory." (PMID 21637513, 2009). "Additionally, miR-194-5p directly targeted the TLR4 gene, regulating cytokine production in response to Salmonella infection." (PMID 40871238, 2025). "Similar profiles of TLR4 and MyD88 in the piglet groups in the ileum and mesenteric lymph nodes attest to MyD88 as the main adaptor molecule mediated inflammatory signaling in the Salmonella infection." (PMID 36768650, 2023). "In addition, we also observed that challenging Salmonella significantly enhanced the mRNA expressions of TLR4 and NF-ΚB; protein expressions of TLR4 and p-NF-ΚB/NF-ΚB were also higher in the Salmonella infection group compared with the control group." (PMID 35163196, 2022). "However, EPS treatment and the pretreatment of IPEC-J2 cells up-regulated the mRNA transcriptional level of TLR4, although compared with the Salmonella infection it was still significantly lower." (PMID 36556320, 2022). "However, previous studies also reported an increase in TLR4 mRNA expression that was induced by Salmonella infection." (PMID 34944274, 2021). "Upon salmonella infection, LPS serves as an inflammatory agent that is stimulated by TLR4." (PMID 34512716, 2021). "Interestingly, the apoptotic response to Salmonella was considerably reduced in BMDMs from TLR4-deficient mice, indicating that PKR is required for TLR4-dependent apoptosis during Salmonella infection." (PMID 34305942, 2021). "TLR4, MyD88, and interleukin (IL) 8 increase after Salmonella infection." (PMID 32075044, 2020). "The polymorphic locus G247A of TLR4 is significantly associated with resistance to Salmonella in specific pathogenic free (SPF) white leghorn chickens, and Nod1 expression is upregulated in blood and spleen after Salmonella infection." (PMID 32075044, 2020). "The result suggests the linkage of TLR4/NF-κB pathway may involved in the suppression of C. butyricum on Salmonella infection." (PMID 32180765, 2020). "TLR-4 is a pattern recognition receptor and recognizes the lipopolysaccharide of gram-negative bacteria and is an indicator of immune stimulation following Salmonella infection." (PMID 31600299, 2019). "Besides the physical barrier, Toll-like receptors (TLRs) on the cell membrane, especially TLR4, play an essential role in the recognition and defense against Salmonella infection." (PMID 31795199, 2019). "Moreover, susceptible chickens have been reported to have an increased methylation level of the TLR4 gene after Salmonella infection." (PMID 26497311, 2015). "It is also possible that the addition of Ara4N to the phosphate groups present on the lipid A portion of LPS alters the ability of Toll-like receptor 4 (TLR4) to recognize and respond to LPS, and ultimately interferes with the ability of the immune sytem to clear Salmonella infection." (PMID 23166721, 2012). "Also, innate immune recognition via TLR4 was reported to play a significant role in the host defense against Salmonella infection in vivo." (PMID 19730692, 2009). "Given the importance of this signaling route in Salmonella infection, and its previously shown over-activation in S. Typhimurium-infected porcine ileum, we hypothesized that miR-194 could be directly regulating the TLR4 signaling pathway." (PMID 35598011, 2022).